SHCBP1 (SHC binding and spindle associated 1)
Description:
May play a role in signaling pathways governing cellular proliferation, cell growth and differentiation. May be a component of a novel signaling pathway downstream of Shc. Acts as a positive regulator of FGF signaling in neural progenitor cells.
Synonyms: FLJ22009; PAL
Tractability: PROTAC: ubiquitination databases record sites on it.
Gene: Protein-coding gene on chromosome 16 (46,578,591 to 46,621,379, reverse strand). Ensembl gene ENSG00000171241.
Subcellular location: Midbody; Cytoplasm, cytoskeleton, spindle
Subcellular location (Human Protein Atlas): Nuclear bodies; Microtubules; Midbody; Mitotic spindle
Gene Ontology:
Molecular function: protein binding; SH2 domain binding
Biological process: fibroblast growth factor receptor signaling pathway; regulation of neural precursor cell proliferation
Cellular component: midbody; mitotic spindle; spindle
Genetic constraint (gnomAD): Loss-of-function variants: 53 observed, 65.56 expected, observed/expected ratio (o/e) 0.81, 90% interval 0.65 to 1.02. The upper end of that interval is the gene's LOEUF score, 1.02, which puts it in group 4 of 6, group 1 being the genes least tolerant of losing a copy. Missense variants: 676 observed, 804.85 expected, observed/expected ratio (o/e) 0.84, 90% interval 0.79 to 0.89. Synonymous variants: 278 observed, 296.29 expected, observed/expected ratio (o/e) 0.94, 90% interval 0.85 to 1.04.
Homologues: Orthologues: chimpanzee SHCBP1 (99% identical), macaque SHCBP1 (98% identical), pig SHCBP1 (90% identical), rabbit SHCBP1 (90% identical), dog SHCBP1 (88% identical), guinea pig SHCBP1 (84% identical), mouse Shcbp1 (78% identical), rat Shcbp1 (78% identical). Paralogues in human: SHCBP1L (25% identical).
Diseases named in the same sentence as SHCBP1 in open-access papers:
SHCBP1 is named in the same sentence as 69 diseases in open-access papers, as found by Europe PMC text mining. Sharing a sentence is not in itself a finding about the gene and the disease. The quoted sentences say what the papers report.
breast carcinoma (24 papers, 2016 to 2025). "Incorporation of SHCBP1 into ceRNA and lactylation–associated regulatory networks has further enhanced its value for identifying subgroups of high-risk breast cancer patients who are less responsive to therapy." (PMID 41009347, 2025). "Chromatin immunoprecipitation assays performed in breast cancer cells have shown direct association of the histone methyltransferase SMYD3 with the SHCBP1 promoter, facilitating transcriptional induction through H3K4me3 modification." (PMID 41009347, 2025). "We previously reported that a 4-gene score derived from the tumor expression of DOK4, HCCS, PGF, and SHCBP1 genes is associated with tumor aggressiveness and can be considered as a potential predictive biomarker for breast cancer." (PMID 32650578, 2020). "Here, we found that SHCBP1 deficiency inhibited the proliferation of breast cancer cells." (PMID 38021148, 2023). "As SHCBP1 is repeatedly recognized as a key component in multi-gene prognostic models in several studies, its expression may function as a reliable biomarker for differentiating breast cancer patient risk and informing personalized treatment plans." (PMID 41009347, 2025). "Comparable findings have been observed in breast cancer cells, where SHCBP1 knockdown led to ERK1/2 pathway inhibition and CXCL2 upregulation, contributing to decreased colony formation and cell viability." (PMID 41009347, 2025). "In breast cancer, SHCBP1 also modulates the immunosuppressive TME by upregulating immune checkpoint gene expression and changing patterns of immune cell infiltration." (PMID 41009347, 2025). "For instance, ShcA, which interacts with SHCBP1, has been demonstrated to enhance both glycolysis and mitochondrial respiration in breast cancer cells through RTK-dependent activation and upregulation of PGC-1α, a central regulator of mitochondrial biogenesis." (PMID 41009347, 2025). "Increased SHCBP1 expression is detected in a wide range of tumors, including breast cancer, non-small-cell lung carcinoma (NSCLC), gastric adenocarcinoma, hepatocellular carcinoma (HCC), leukemias, gliomas, and cutaneous cancers." (PMID 41009347, 2025). "Comparable patterns have been reported in breast cancer, where SHCBP1 modulates the levels of PUMA and BCL2 to enhance cell survival." (PMID 41009347, 2025). "In breast cancer, upregulation of SHCBP1 correlates with suppression of CDKN1A (p21) and CDKN1B (p27), which are crucial inhibitors of CDK activity." (PMID 41009347, 2025). "Despite these findings, the role of SHCBP1 in breast cancer, especially in TNBC, remains poorly understood." (PMID 40799237, 2025). "Quantitative PCR (qPCR) and western blotting were employed to measure SHCBP1 expression in breast cancer cell lines." (PMID 40799237, 2025). "In breast cancer, elevated SHCBP1 expression correlates with advanced clinical stages and poor prognosis." (PMID 40799237, 2025). "We found that low-SHCBP1 breast cancer had favorable clinical characteristics, such as more T1 (27% vs. 16%) and N0 (66.7% vs. 57.1%)." (PMID 40799237, 2025). "In breast cancer, both SHCBP1 mRNA and protein levels are significantly higher in tumor tissues when compared to normal tissue counterparts." (PMID 41009347, 2025). "In breast cancer, the alteration frequency of SHCBP1 was found to be 3%, with 27 cases showing amplification and 2 cases exhibiting a missense mutation." (PMID 40799237, 2025). "Similar results were obtained in the present study, with abnormally high expression of SHCBP1 in breast cancer tissues and cells, and its upregulation level was correlated with the clinicopathologic staging of breast cancer and the survival rate of patients." (PMID 38021148, 2023). "We conducted a search on the DepMap Portal to assess the expression levels of TMEM45A and SHCBP1 in various breast cancer cell lines." (PMID 38035071, 2023). "Immunohistochemistry showed that SHCBP1 was mainly distributed in the nucleus and exhibited a high expression level in breast cancer tissues." (PMID 38021148, 2023).
breast carcinoma (continued). "Intriguingly, the survival rate of patients was closely related to the expression level of SHCBP1 during the breast cancer survival curve over time (HR=1.59, P=1.5e-06)." (PMID 38021148, 2023). "Immunofluorescence staining showed that SHCBP1 was highly expressed in the nucleus of MCF-7 cells, which was consistent with the localized expression of SHCBP1 in breast cancer tissues." (PMID 38021148, 2023). "To further investigate the biological function of SHCBP1 in breast cancer cells, we knocked down SHCBP1 in MCF-7 cell lines, and the efficiency of SHCBP1 knockdown was 68% (P<0.01)." (PMID 38021148, 2023). "The stronger the expression of SHCBP1 protein in breast cancer tissues, the later the clinical stage and the shorter the survival period of the patients." (PMID 36920183, 2023). "Meanwhile, we found that the expression level of SHCBP1 was correlated with the clinical stage of breast cancer, with the highest expression in stage II (P<0.01)." (PMID 38021148, 2023). "As expected, the CCK-8 assay showed that the knockdown of TMEM45A and SHCBP1 in MDAMB468 similarly inhibited the proliferation of breast cancer cells." (PMID 38035071, 2023). "SHCBP1 is involved in intracellular signal transduction and cell division, which is highly expressed in lung cancer, breast cancer, liver cancer and other tumor cells, and promotes tumor cell proliferation." (PMID 38005336, 2023). "Previous studies have shown that SHCBP1 is highly expressed in many malignant tumors such as breast cancer, lung cancer, and glioma." (PMID 38005336, 2023). "To further confirm the database results, we detected that the protein expression of SHCBP1 was highest in breast cancer tissues by Western blotting." (PMID 38021148, 2023). "We further investigated the impact of TMEM45A and SHCBP1 knockdown on the functionality of breast cancer cells through CCK-8 and colony formation assays to determine their effects on BRCA cell proliferation." (PMID 38035071, 2023). "The phenomenon of overexpression of SHCBP1 in breast cancer has been studied, and cellular experiments have demonstrated that this gene directly regulates breast cancer cell proliferation and promotes the cell cycle." (PMID 36267313, 2022). "The expressions of KIF4A, RACGAP1, CKS2, SHCBP1, and HMMR were high in breast cancer, associated with poor OS and different breast cancer subclasses." (PMID 33959662, 2021). "SHCBP1 is involved in the development of hepatocellular carcinoma, glioma, breast cancer, and gastric cancer." (PMID 32351983, 2020). "SHCBP1 expression was higher in breast cancer compared with adjusted tissue and it correlated with worse cancer stage and poor survival." (PMID 32370309, 2020). "Studies have also shown that SHCBP1 is involved in the development of various tumors such as hepatocellular carcinoma, glioma, breast cancer, and gastric cancer." (PMID 32351983, 2020). "This is consistent with the results of SHCBP1 activity in hepatocellular carcinoma cells and breast cancer cells, where it regulates cell cycle; SHCBP1 also regulates cell migration via EMT receptor interactions in synovial sarcoma cells." (PMID 32351983, 2020). "SHCBP1 is shown to be significantly up-regulated in breast cancer tissues compared with adjacent normal tissues, and its overexpression is correlated with advanced clinical stage and poorer survival." (PMID 27857161, 2016). "In breast cancer, SHCBP1 has been shown highly expressed in tumor samples and is correlated with metastatic potential, advanced stage, and poor prognosis." (PMID 27572315, 2016). "Similarly, combined administration of trametinib and αPD-1 antibody inhibited SMYD3/SHCBP1-dependent breast cancer progression in xenografts by suppressing MEK activation and promoting CD4/8+ cell infiltration." (PMID 41009347, 2025).
breast carcinoma (continued). "Similarly, conditional SHCBP1 deletion in mammary epithelial cells using MMTV-Cre transgenic mice markedly slowed breast cancer development and metastasis through restored Rab8-mediated ciliogenesis." (PMID 41009347, 2025). "Importantly, SHCBP1 is commonly identified as part of multi-gene prognostic signatures for breast cancer patients." (PMID 41009347, 2025). "In contrast to SHCBP1, breast cancer patients with low CXCL2 expression had poor overall survival." (PMID 38021148, 2023). "In summary, we speculate that SHCBP1 may play an important role in intracellular signal transduction and cell division in breast cancer cells." (PMID 38021148, 2023). "Collectively, our study reveals that SHCBP1 plays an oncogenic role in breast cancer tumorigenesis partially through inhibiting the inflammatory response and ultimately activating the proliferation of breast cancers." (PMID 38021148, 2023). "As expected, the SHCBP1 expression is negatively correlated with the expression of CXCL2 in breast cancer cell (P<0.01), suggesting that CXCL2 may play an important role in the proliferation of MCF-7 cells regulated by SHCBP1." (PMID 38021148, 2023). "Whether SHCBP1 is a new oncogene in the malignant process of breast cancer still needs to be further studied." (PMID 38021148, 2023). "TCGA and GEO data analyses revealed that TMEM45A and SHCBP1 were highly expressed in breast cancer." (PMID 38035071, 2023). "Is CXCL2 involved in the regulation of breast cancer cell proliferation by SHCBP1?" (PMID 38021148, 2023). "To determine whether and how SHCBP1 affects the proliferation of breast cancer, we analyzed the expression abundance of SHCBP1 in breast cancer tissues and normal breast tissues from the GEPIA database." (PMID 38021148, 2023). "Thus, is the involvement of SHCBP1 in the regulation of breast cancer cell proliferation closely related to the occurrence of inflammation?" (PMID 38021148, 2023). "Hence, in breast cancer, is the regulation of breast cancer cell proliferation by SHCBP1 mediated by inflammatory cytokines?" (PMID 38021148, 2023). "It is clear that SHCBP1 is involved in the regulation of the occurrence and development of breast cancer by inhibiting the autoinflammatory response of breast cancer cells, which provides an experimental basis for the early diagnosis and treatment of breast cancer." (PMID 38021148, 2023). "Notably, the SHCBP1 mRNA expression levels were significantly elevated in breast cancer tissues (P<0.05)." (PMID 38021148, 2023). "SHCBP1 regulates breast cancer cell proliferation through apoptosis and cell cycle regulation." (PMID 32370309, 2020). "Immunohistochemical analysis revealed that SHCBP1 was upregulated in breast cancer." (PMID 31007608, 2019). "Studies have shown that SHCBP1 was upregulated in breast cancer tissues and cells and could promote breast cancer cell proliferation and inhibit apoptosis." (PMID 31427569, 2019). "Similarly, high SHCBP1 also indicate a shorter RFS in breast cancer (GSE30682), another common cancer of epithelial origin, and liposarcoma (GSE30929), a malignant tumor of mesodermal origin." (PMID 30177836, 2019). "Notably, it was shown that SHCBP1 was significantly up-regulated in breast cancer tissues, and that SHCBP1 knockout inhibited cell proliferation, thus supporting the hypothesis that SHCBP1 is an oncogene." (PMID 35886011, 2022). "SHCBP1 mRNA expression was significantly higher in TNBC and Her2-positive breast cancer (BC) compared with luminal A and luminal B subtypes." (PMID 40799237, 2025). "In breast cancer models, CAF–specific SHCBP1 knockout enhanced the antitumor activity of Erdafitinib and PD-1 blockade, largely by influencing immune cell recruitment and inhibiting CAF activity." (PMID 41009347, 2025). "Next, we explored the correlation between SHCBP1 and CXCL2 expression in breast cancer using the GEPIA database." (PMID 38021148, 2023).
breast carcinoma (continued). "Shc SH2-domain binding protein 1 (SHCBP1) is an important protein in intracellular signal transduction and cell division, but the role of SHCBP1 in breast cancers remains elusive." (PMID 38021148, 2023). "To clarify the clinical significance of SHCBP1 and ORC6, we carried out a survival prediction analysis of these genes using Affymetrix microarray expression profiles in 4934 breast cancer patients available in the Kaplan–Meier (K–M) plotter." (PMID 35886011, 2022). "Previous studies also demonstrated the oncogenic role of SHCBP1 in non-small cell lung carcinoma (NSCLC) and breast cancer." (PMID 33990570, 2021). "For validation in UALCAN, GEPIA, and KM, 5 core genes (KIF4A, RACGAP1, CKS2, SHCBP1, and HMMR) were found to highly expressed in breast cancer tissues with poor prognosis." (PMID 33959662, 2021). "In addition to NSCLC, SHCBP1 was also widely up-regulated in breast cancer, glioma and hepatocellular carcinoma (HCC), as shown by our analyses of the GEO datasets (GSE4290, GSE45114, and GSE29174), suggesting that aberrant expression of SHCBP1 might be a common event in human cancers." (PMID 30177836, 2019). "SHCBP1, a new signaling pathway downstream of SHC adaptor proteins, is frequently found to be upregulated in several human malignancies including breast cancer, hepatocellular carcinoma, and certain leukemia/lymphoma." (PMID 27572315, 2016). "Notably, SHCBP1 knockout in mice improves the efficacy of combination therapy with Erdafitinib and anti-PD1 antibody in breast cancer models." (PMID 41009347, 2025). "Smyd3-Shcbp1 expression could be reversed by trametinib treatment, and the combinatory treatment of trametinib with αPD1 enhances the function of effector T cells and sensitizes mammary tumors with elevated SMYD3 and SHCBP1 to αPD1 treatment." (PMID 40157910, 2025). "To test this hypothesis, we used the HP (HP5712) cell line, which was derived from a spontaneous mammary tumor in an FVB female mouse with relatively high protein levels of both Smyd3 and Shcbp1." (PMID 40157910, 2025). "Therefore, we knocked down TMEM45A and SHCBP1 and further investigated the role of TMEM45A and SHCBP1 in MDA-MB-468 breast cancer cells in vitro." (PMID 38035071, 2023). "We propose that SHCBP1 and ORC6 are novel oncogenes involved in breast cancer development." (PMID 35886011, 2022). "We hypothesized that the observed structural variation breakpoints in MCF7 cells, and observed over-expression of SHCBP1 and ORC6, affect the outcomes of breast cancer patients whose primary tumors are ER-positive." (PMID 35886011, 2022). "Therefore, we suggest that SHCBP1 and ORC6 are prime targets for anti-cancer interventions in breast cancer treatment." (PMID 35886011, 2022). "Importantly, two of the over-expressed genes, SHCBP1 and ORC6, in this cluster also show significantly increased expression in breast cancer tissues reported in TCGA." (PMID 35886011, 2022). "CKS2, KIF4A, RACGAP1, and SHCBP1 all have positive correlation with HMMR; they may become combined indicator of prognosis or targets for different subtypes of breast cancer." (PMID 33959662, 2021). "These five genes (KIF4A, RACGAP1, CKS2, SHCBP1, and HMMR) could be potential targets for therapy in breast cancer and prediction of prognosis on the basis of bioinformatical analysis." (PMID 33959662, 2021). "First, although high expressions of KIF4A, RACGAP1, CKS2, SHCBP1, and HMMR were independent prognostic factors of poor OS of breast cancer, all the data in our research came from online database and we need further experiments in vitro and in vivo to validate our findings." (PMID 33959662, 2021). "SHCBP1 (SHC SH2-binding protein 1), a member of Src homolog and collagen homolog family, has been reported to be over-expressed in several malignancies including breast cancer." (PMID 32370309, 2020).
breast carcinoma (continued). "As we previously reported, the four-gene score has reflected cell proliferation in breast cancer by measuring gene expressions of DOK4, HCCS, SHCBP1, and PGF; it was of interest to investigate the distribution of the score in other types of cancer in The Cancer Genome Atlas (TCGA) project." (PMID 33291601, 2020). "Notably, SHCBP1 is highly expressed in breast cancer tissues and cells, but the biological function and mechanism of SHCBP1 in breast cancer cells are not clear." (PMID 38021148, 2023).